FLRT2 (fibronectin leucine rich transmembrane protein 2)
Description:
Functions in cell-cell adhesion, cell migration and axon guidance. Mediates cell-cell adhesion via its interactions with ADGRL3 and probably also other latrophilins that are expressed at the surface of adjacent cells. May play a role in the migration of cortical neurons during brain development via its interaction with UNC5D. Mediates axon growth cone collapse and plays a repulsive role in neuron guidance via its interaction with UNC5D, and possibly also other UNC-5 family members. Plays a role in fibroblast growth factor-mediated signaling cascades. Required for normal organization of the cardiac basement membrane during embryogenesis, and for normal embryonic epicardium and heart morphogenesis.
Tractability: Small molecule: it belongs to a druggable protein family. Antibody: its Gene Ontology location is reachable by antibodies, with high confidence; UniProt places it where antibodies can reach, with medium confidence; UniProt predicts a signal peptide or a membrane-spanning region. PROTAC: its protein half-life has been measured.
Gene: Protein-coding gene on chromosome 14 (85,530,017 to 85,654,428, forward strand). Ensembl gene ENSG00000185070.
Subcellular location: Cell membrane; Endoplasmic reticulum membrane; Cell junction, focal adhesion; Secreted, extracellular space, extracellular matrix; Microsome membrane; Secreted; Synapse, synaptosome
Pathways (Reactome):
Signal Transduction: Downstream signaling of activated FGFR1
Gene Ontology:
Molecular function: protein-macromolecule adaptor activity; chemorepellent activity; fibroblast growth factor receptor binding
Biological process: basement membrane organization; cell adhesion involved in heart morphogenesis; fibroblast growth factor receptor signaling pathway; heart morphogenesis; negative chemotaxis
Cellular component: extracellular exosome; focal adhesion; cell-cell junction; endoplasmic reticulum membrane; extracellular matrix; extracellular region; plasma membrane; glutamatergic synapse; postsynaptic membrane; presynaptic membrane; synapse
Genetic constraint (gnomAD): Loss-of-function variants: 15 observed, 39.62 expected, observed/expected ratio (o/e) 0.38, 90% interval 0.25 to 0.58. The upper end of that interval is the gene's LOEUF score, 0.58, which puts it in group 2 of 6, group 1 being the genes least tolerant of losing a copy. Missense variants: 726 observed, 853.51 expected, observed/expected ratio (o/e) 0.85, 90% interval 0.8 to 0.9. Synonymous variants: 380 observed, 340.81 expected, observed/expected ratio (o/e) 1.12, 90% interval 1.02 to 1.21.
Homologues: Orthologues: chimpanzee FLRT2 (99% identical), macaque FLRT2 (99% identical), mouse Flrt2 (97% identical), rabbit FLRT2 (97% identical), guinea pig FLRT2 (97% identical), dog FLRT2 (97% identical), rat Flrt2 (96% identical), pig FLRT2 (95% identical), tropical clawed frog flrt2 (79% identical), zebrafish flrt2 (62% identical). Paralogues in human: FLRT3 (45% identical), FLRT1 (42% identical), LRRC4C (21% identical), LRRC15 (20% identical), LRRC4B (20% identical), LRRC4 (19% identical), LRRTM3 (18% identical), LRRTM4 (17% identical), PODNL1 (17% identical), PODN (17% identical), GP1BA (16% identical), RTN4R (16% identical), and 10 more.
Diseases named in the same sentence as FLRT2 in open-access papers:
FLRT2 is named in the same sentence as 46 diseases in open-access papers, as found by Europe PMC text mining. Sharing a sentence is not in itself a finding about the gene and the disease. The quoted sentences say what the papers report.
breast carcinoma (11 papers, 2014 to 2026). "The authors demonstrated that FLRT2 was implicated in breast cancer progression, specifically, the downregulation of FLRT2 was associated with inactivated hypermethylation during tumor formation causing increased proliferation and cell migration in breast cancer." (PMID 39596804, 2024). "FLRT2 has been implicated in differentially regulated processes between males and females, such as prostate cancer and several primarily female and hormone-related physiological and pathophysiological processes in humans, including menarche and breast cancer." (PMID 39596804, 2024). "Contrarily, FLRT2 downregulation was observed in colorectal cancer and breast cancer, and FLRT2 inhibited colorectal cancer and breast cancer progression." (PMID 39444619, 2024). "have found that FLRT2 is highly methylated in breast cancer patient tissue and inhibits the proliferation, migration, and adhesion of the breast cancer cells." (PMID 37090697, 2023). "In breast cancer, FLRT2 has been identified as a tumor suppressor gene, and interestingly, LOC124907389 exhibited a twofold downregulation in patient-derived glioma tissue." (PMID 37872607, 2023). "In silico screening of human breast cancer cells showed that FLRT2 is one of the most hypermethylated and downregulated genes, suggesting epigenetic regulation of FLRT2 in endothelial cells." (PMID 35104247, 2022). "The aim of this study was to develop methylation markers through in silico meta-data analysis, and this revealed FLRT2 to be hypermethylated in breast cancer." (PMID 28325946, 2017). "Taken together, it has been shown in this study that FLRT2 expression is suppressed in breast cancer as a result of hypermethylation at promoter CpG sites, which is related to an unfavorable prognosis in cancer patients." (PMID 28325946, 2017). "This pilot study repeatedly displayed hypermethylation and downregulation patterns of FLRT2 in breast cancer cells in silico." (PMID 28325946, 2017). "FLRT2 was found to be downregulated in all examined breast cancer cell lines, MCF-7, T47D, MDA-MB-231, HCC38, and HCC1395, compared to normal cell line MCF-10A." (PMID 28325946, 2017). "The combined results of in silico and molecular experiments suggest that FLRT2 is potentially an epigenetically modulated tumor suppressor in breast cancer." (PMID 28325946, 2017). "In breast cancer, FLRT2 and SCTR are good candidates for novel markers; the expression of which is known to be down regulated." (PMID 24842468, 2014). "Flrt2 has novel tumor suppressor activity in breast cancer and localizes to pre- and post-synapses in the postnatal developing hippocampus where it may play a role in synapse formation." (PMID 41566221, 2026). "In this study, we used a breast cancer model to examine the effects of radiation alone or in combination with estrogens on the expression of genes linked to cell motility, such as ADAM12, CYR61, FLRT2, SLIT2, VNN1, MYLK, MAP1B, and TUBA1A." (PMID 39596804, 2024). "In addition, FLRT2 has been shown to suppress the viability and invasive capacity of breast cancer cells." (PMID 28325946, 2017). "However, FLRT2 is a tumor suppressor in the liver and breast cancers." (PMID 39444619, 2024). "The results suggest that FLRT2 may have tumor suppressor activity in breast cancer." (PMID 28325946, 2017). "According to a bioinformatic study, the expression of the genes FLRT2, SLIT2, VNN1, MAP1B, MYLK, and TUBA1A was found to be higher in normal tissue than in malignant tissue in patients with breast cancer." (PMID 39596804, 2024). "However, neither the methylation in other cancer tissues, including breast cancer, nor the dysregulation of FLRT2 in cancer has been studied." (PMID 28325946, 2017).
colorectal cancer (8 papers, 2020 to 2025). A primary or metastatic malignant neoplasm that affects the colon or rectum. "The fibronectin leucine-rich transmembrane protein 2 (FLRT2) is known to mediate endothelial adhesion in tumors, potentially enhancing the invasive characteristics of colorectal cancer cells." (PMID 39744172, 2025). "For example, FLRT2 is widely expressed in abnormal blood vessels in advanced colorectal cancer, and its expression is negatively correlated with long-term survival." (PMID 39444619, 2024). "Previous reports also showed that hypermethylation of the FLRT2 promoter led to decreased FLRT2 gene expression, which was involved in the development of prostate, breast, and colorectal cancers." (PMID 37090697, 2023). "Here, we analyzed human colorectal cancer samples and found that FLRT2 is expressed abundantly in endothelial cells lining abnormalized vessels." (PMID 35104247, 2022). "We examined expression of FLRT2 by immunostaining tissues from a cohort of 47 patients with colorectal cancer who had undergone surgical resection." (PMID 35104247, 2022). "Colorectal cancers are epithelial cell–derived malignant tumors that infiltrate the submucosal, muscularis, and serosal layers; therefore, we examined expression of FLRT2 in superficial and progressive areas." (PMID 35104247, 2022). "Taken together, these data suggest that expression of FLRT2 is an independent biomarker for predicting prognosis of colorectal cancers (in addition to canonical staging)." (PMID 35104247, 2022). "Here, we found that an axon guidance molecule, fibronectin leucine-rich transmembrane protein 2 (FLRT2), is expressed preferentially in abnormalized vessels of advanced colorectal cancers in humans and that its expression correlates negatively with long-term survival." (PMID 35104247, 2022). "FLRT2 is expressed in the tumor endothelial cells of advanced human colorectal cancers." (PMID 35104247, 2022). "Our data also suggest that FLRT2 is possibly a novel theranostic molecule with potential utility as an effective and less harmful therapeutic target and/or as a biomarker for the long-term prognosis of patients with colorectal cancer." (PMID 35104247, 2022). "In colorectal cancer, FLRT2 formed noncanonical inter-endothelial adhesions that safeguarded against oxidative stress through homophilic binding." (PMID 40810103, 2025). "Because these results suggest that expression of endothelial FLRT2 is related to long-term prognosis, we examined another cohort of 66 patients who underwent curative surgical resection for pathological stage II or III colorectal cancer and were followed up for 5 years." (PMID 35104247, 2022).
prostate carcinoma (4 papers, 2017 to 2023). A carcinoma that arises from epithelial cells of the prostate gland. "FLRT2 is involved in the development of ovarian and uterine carcinogenesis, and FLRT2 has been reported to be a tumor suppressor in breast and prostate cancer." (PMID 34512722, 2021). "The gene FLRT2 is believed to have a role in tumor suppression in breast and prostate cancers, and in mouse models, FLRT2 has been found as a guiding agent in neuronal and vascular cells." (PMID 33643374, 2021).
bladder cancer (3 papers, 2023 to 2025). "Then, RNA‐sequencing was performed to clarify the underlying mechanism by which FLRT2 regulated the tumorigenesis of human bladder cancer." (PMID 37480224, 2023). "Fibronectin leucine rich transmembrane protein 2 (FLRT2) is associated with the regulation of multiple tumours; however, its function in human bladder cancer remain unclear." (PMID 37480224, 2023). "In cisplatin-resistant bladder cancer cell lines, FLRT2, HOXC5, SCD, GRM7, HMGA1, ETV7, and SCO2 were highly expressed, while EMP1, SERPINA6, and ZNF124 exhibited lower expression levels." (PMID 39744172, 2025). "Consistently, we also found that human bladder cancer tissues displayed lower protein levels of FLRT2." (PMID 37480224, 2023). "Overall, we demonstrate that FLRT2 suppresses bladder cancer progression through inducing ACSL4‐mediated ferroptosis." (PMID 37480224, 2023). "We herein demonstrated that FLRT2 overexpression facilitated ferroptosis of bladder cancer cells, thereby inhibiting tumour cell proliferation, migration and invasion." (PMID 37480224, 2023). "Collectively, we demonstrate that FLRT2 silence facilitates the malignant phenotypes of human bladder cancer cells." (PMID 37480224, 2023). "Unexpectedly, GSH level and GPX4 activity were slightly but significantly elevated in FLRT2‐overexpressed bladder cancer cells, suggesting a compensatory protection of GSH/GPX4." (PMID 37480224, 2023). "Collectively, we demonstrate that FLRT2 overexpression promotes ferroptosis of human bladder cancer cells." (PMID 37480224, 2023). "Herein, we found that FLRT2 level was reduced in human bladder cancer and that higher FLRT2 level predicted lower survival rate." (PMID 37480224, 2023). "Collectively, we demonstrate that FLRT2 overexpression inhibits the malignant phenotypes of human bladder cancer cells." (PMID 37480224, 2023). "Collectively, our findings reveal that FLRT2 expression is reduced in human bladder cancer and negatively correlates with patients survival." (PMID 37480224, 2023). "In this study, FLRT2 expression was found to be reduced in human bladder cancer, and higher FLRT2 level predicted lower survival rate." (PMID 37480224, 2023). "Collectively, we demonstrate that FLRT2 silences suppresses ferroptosis of human bladder cancer cells." (PMID 37480224, 2023). "Herein, we intend to explore the function of FLRT2 in bladder cancer." (PMID 37480224, 2023). "Besides, protein quantification assay also detected a decreased FLRT2 protein in bladder cancer cells compared with the normal SV‐HUC‐1 cell." (PMID 37480224, 2023). "Yet, GSH level and GPX4 activity were unaffected by FLRT2 silence in human bladder cancer cells." (PMID 37480224, 2023). "Leucine-rich repeat transmembrane protein FLRT2 (FC = 8.891, p = 5.15E-03) promotes lipid peroxidation by increasing the expression of acyl-CoA synthetase long-chain family member 4, thereby triggering ferroptosis and inhibiting the malignant phenotype of human bladder cancer cells." (PMID 40709343, 2025). "Mechanistic studies revealed that FLRT2 elevated ACSL4 expression, increased lipid peroxidation and subsequently facilitated ferroptosis of human bladder cancer cells." (PMID 37480224, 2023). "As expected, FLRT2 overexpression significantly increased the levels of ROS and MDA in human bladder cancer cells." (PMID 37480224, 2023). "FLRT2 overexpression elevated, while FLRT2 silence reduced ACSL4 protein expression in human bladder cancer cells." (PMID 37480224, 2023). "In contrast, FLRT2 silence significantly decreased the levels of ROS and MDA in human bladder cancer cells." (PMID 37480224, 2023). "We demonstrate that FLRT2 elevates ACSL4 expression and subsequently facilitates lipid peroxidation and ferroptosis, thereby inhibiting the malignant phenotype of human bladder cancer cells." (PMID 37480224, 2023).
bladder cancer (continued). "Mechanistic studies revealed that FLRT2 elevated acyl‐CoA synthetase long‐chain family member 4 (ACSL4) expression, increased lipid peroxidation and subsequently facilitated ferroptosis of human bladder cancer cells." (PMID 37480224, 2023). "In summary, we demonstrate that FLRT2 elevates ACSL4 expression to facilitate lipid peroxidation and subsequently triggers ferroptosis, thereby inhibiting the malignant phenotype of human bladder cancer cells." (PMID 37480224, 2023). "Iron overload contributes to ferroptosis; yet, our findings showed that FLRT2 did not affect intracellular iron level in human bladder cancer cells." (PMID 37480224, 2023).
lung carcinoma (2 papers, 2017 to 2024). "Based on the online Kaplan-Meier plotter (Győrffy, 2024), patients with relatively higher FLRT2 expression displayed longer survival durations, implying that FLRT2 was positively associated with lung cancer prognosis." (PMID 39444619, 2024). "FLRT2 exhibited a significant reduction in all lung cancer cell lines from mRNA and protein levels compared to BEAS-2B cells." (PMID 39444619, 2024). "FLRT2 abundance was detected in normal lung epithelial cell line BEAS-2B and lung cancer cell lines A549, H1975, NCI-H270, PC-9, and SPCA-1." (PMID 39444619, 2024).
melanoma (2 papers, 2013 to 2022). A malignant, usually aggressive tumor composed of atypical, neoplastic melanocytes. "Next, we used a syngeneic murine B16 melanoma model to evaluate the bona fide role of endothelial FLRT2 in tumor progression." (PMID 35104247, 2022). "Specifically, FLRT2 was downregulated while MAD1L1, PHLDA2, PLAT, CC2D1B, CDKN2A and RUNX3 were upregulated in both melanoma and in Group 2 and Group 3 SFs." (PMID 23371019, 2013). "Because Flrt2 acts primarily as a repulsive ligand for the Unc5b receptor, we injected endothelial cell–specific Unc5b-knockout mice (Cdh5-BAC-CreERT2Unc5bfl/fl; referred to hereafter as Unc5biΔEC mice) with B16 melanoma cells." (PMID 35104247, 2022).
Obesity (2 papers, 2022 to 2025). Accumulation of substantial excess body fat. "Utilizing the BLISS method, we successfully identified 89 proteins implicated in the comorbid risk of obesity and depression across the deCODE, UKBPP, and ARIC databases, with SCG3 and FLRT2 detected in all three." (PMID 40405979, 2025). "Although no direct evidence currently connects FLRT2 to obesity or depression, its integral role in nervous system development underscores its potential as a therapeutic target for psychiatric disorders." (PMID 40405979, 2025).
systemic lupus erythematosus (2 papers, 2013 to 2017). An autoimmune multi-organ disease typically associated with vasculopathy and autoantibody production. "The Leu-rich epitopes have also been shown to induce an IL-17 response in different autoimmune diseases such as NLRP3 (autoimmune encephalomyelitis), FLRT2 (systemic lupus erythematosus), and LGI1 (limbic encephalitis)." (PMID 29163505, 2017).
acute myeloid leukemia (1 paper, 2023). Acute myeloid leukemia (AML) is a group of neoplasms arising from precursor cells committed to the myeloid cell-line differentiation. "By deciphering a novel role for the endogenous membrane protein FLRT2 in promoting monocyte-to-macrophage differentiation, our findings may help develop therapeutic strategies for human diseases with dysregulated monocyte/macrophage differentiation, such as acute myeloid leukemia (AML)." (PMID 37090697, 2023).
atherosclerosis (1 paper, 2023). A disease characterized by the build-up of fatty material and calcium deposition in the arterial wall resulting in partial or complete occlusion of the arterial lumen. "Experimental manipulation of DNA methylation in engineered human umbilical vein endothelial cells indicated that the identified differentially methylated probes located at TRIM6, TLN2, and FLRT2 genes may play a role in endothelial cell adhesion and atherosclerosis." (PMID 37370144, 2023).
bladder tumor (1 paper, 2025). "Notably, FLRT2 and LPA were significantly upregulated in bladder tumor cell lines compared to normal bladder cells, suggesting a role in tumor progression." (PMID 39744172, 2025).
breast tumor (1 paper, 2024). "However, CYR61, FLRT2, SLIT2, VNN1, MAP1B, MYLK, and TUBA1A gene expressions were high in normal adjacent tissue in comparison with those in breast tumor tissue." (PMID 39596804, 2024).
collagen diseases (1 paper, 2012). "Analysis of anti-FLRT2 activity among patients with various collagen diseases indicated that anti-FLRT2 antibody was specifically detected in SLE, and it accounted for 21.4% of cell-surface target molecules of AECAs in SLE." (PMID 22747982, 2012).
colon adenocarcinoma (1 paper, 2020). "Further, genomic analysis of publicly available MethHC databases revealed that the methylation levels of FLRT2 were remarkably increased in colon adenocarcinoma (COAD) and rectum adenocarcinoma (READ) tissues." (PMID 33193897, 2020).
colon cancers (1 paper, 2022). "One of the most important aspects of our findings is that FLRT2 is expressed abundantly in the abnormalized vessels of advanced human colon cancers." (PMID 35104247, 2022).
epilepsy (1 paper, 2023). A brain disorder characterized by episodes of abnormally increased neuronal discharge resulting in transient episodes of sensory or motor neurological dysfunction, or psychic dysfunction. "The MR analyses also implicated FLRT2 and RARRES2 in epilepsy." (PMID 36504281, 2023). "We also observed two protein‐pQTL pairs (FLRT2‐rs17646457 and RARRES2‐rs3735172) with shared effects with focal epilepsy, as well as hippocampal sclerosis‐related epilepsy." (PMID 36504281, 2023).